FASN (fatty acid synthase)
Diseases named in the same sentence as FASN in open-access papers (continued):
Sharing a sentence is not in itself a finding about the gene and the disease.
prostate carcinoma (continued). "Oncomine data-mining analysis revealed that upregulation of FASN was presented in 9 of 20 cancer types, especially in ovarian cancer, bladder cancer, colorectal cancer, and prostate cancer." (PMID 30619288, 2018). "It has been reported that USP2 can regulate and stabilize fatty acid synthase, an aberrantly over-expressed protein in biologically-aggressive prostate cancer cells." (PMID 30319415, 2018). "Recently, several FASN inhibitors were reported to show antitumor effect against breast, ovarian, and prostate cancers in preclinical models." (PMID 30442117, 2018). "Fatty acid synthase (FASN) is an enzyme that controls fatty acid synthesis and has been shown to promote the growth of prostate cancer as a result of AR signaling." (PMID 28208703, 2017). "It has long been accepted that a common phenotype within prostate cancer is the upregulation of FASN activity and is of clinical utility as a pathologic biomarker that is occasionally examined in a special stain." (PMID 28674679, 2017). "EGR1 and the lipogenic enzyme fatty acid synthase (FASN) are elevated in tissues adjacent to prostate cancer; this relationship is used as a predictive marker of recurrence." (PMID 29228577, 2017). "SREBP1 is stimulated by androgen signaling and epidermal growth factor and has been found to be overexpressed in prostate cancer, leading to the upregulation of FASN." (PMID 28674679, 2017). "It is believed by some that unregulated FASN activity within prostate tissue is itself the beginning of malignant phenotype and has been argued to be necessary for prostate cancer growth maintenance." (PMID 28674679, 2017). "As a key enzyme for FA synthesis fatty acid synthase (FASN) is often overexpressed in human prostate cancers and its expression correlates with worse prognosis and poor survival." (PMID 26934656, 2016). "Since increased fatty acid metabolism characterizes prostate cancer, the correlation between FASN expression and fatty acid content vanishes." (PMID 26623558, 2016). "This was consistent with the increased expression of FASN, both on mRNA and on protein levels in prostate cancer." (PMID 26623558, 2016). "We demonstrated that there is increasing Cav-1, ACC1 and FASN expression during prostate cancer progression (P<0.0001, P=0.007 or P<0.0001 respectively based on Fisher's exact test)." (PMID 27331874, 2016). "In this study, we discovered that FASN inhibition prevented pseudopodia formation and suppressed cell adhesion, migration, and invasion in prostate cancer cells." (PMID 23741342, 2013). "Forced expression of FASN promoted proliferation while siRNA knockdown of FASN induced apoptosis in prostate cancer cells." (PMID 23785446, 2013). "Forced expression of fatty acid synthase (FAS) promoted proliferation while siRNA knockdown of FASN induced apoptosis in prostate cancer cells." (PMID 24349321, 2013). "To examine mechanisms, we established FASN knockdown prostate cancer cells by transduction of short-hairpin RNA against FASN and investigated the characteristics by analyses on morphology and cell behavior and microarray-based gene expression profiling." (PMID 23741342, 2013). "Because of the frequency and variation of FASN overexpression in prostate cancer, it is necessary to predict therapeutic outcomes before application of FASN-targeted therapy to avoid ineffective treatment." (PMID 23741342, 2013). "In fact, it has been reported that inhibitors of FASN, including orlistat, can reduce radiolabeled acetate incorporation into fatty acids in prostate cancer cells." (PMID 23741342, 2013). "Here, we showed the method to predict FASN-targeted therapy outcome using radiolabeled acetate uptake and presented mechanisms of FASN inhibition with human prostate cancer cell lines, to provide the treatment strategy of FASN-targeted therapy." (PMID 23741342, 2013).
prostate carcinoma (continued). "In this study, we demonstrated that uptake of radiolabeled acetate can predict therapeutic outcome of the FASN-targeted therapy in prostate cancer; it was particularly successful for prostate cancer with high acetate uptake." (PMID 23741342, 2013). "Overexpression of FASN is also present in prostate cancers and the FASN expression is related to carcinogenesis, growth, and metastasis, while large variation in FASN expression among individual prostate cancers has been reported." (PMID 23741342, 2013). "Mutations in the CYLD deubiquitinating enzyme leads to familial cylindromatosis and overexpression of USP2 has been reported to increase prostate cancer cell proliferation through the stabilization of fatty acid synthase." (PMID 21264218, 2011). "In contrast, a variety of tumors including breast, colon, ovary, and prostate cancer express elevated FASN levels, since tumor cells become less sensitive to regulatory nutritional signals and prefer the de novo lipogenesis pathway." (PMID 20508725, 2010). "Activated AKT has been shown to increase the expression of FASN in several types of tumors including ovarian and prostate cancers." (PMID 19517019, 2009). "USP2 exhibits oncogenic potential in prostate cancer by stabilizing its substrate Fatty Acid Synthase (FAS), and FAS has indeed been identified as a target of ISG15 modification." (PMID 17653289, 2007). "A promising FASN inhibitor, IPI‐9119, has shown potential in preclinical studies by significantly reducing cell growth, causing cell cycle arrest and triggering apoptosis in prostate cancer cells." (PMID 39973042, 2025). "Additionally, FASN inhibition by triclosan or siRNAs induced apoptosis of LNCaP prostate cancer cells." (PMID 40214422, 2025). "Moreover, studies have demonstrated that FASN inhibition by C75 sensitizes PC-3 and LNCaP prostate cancer cells to the apoptotic and growth-inhibiting effects of radiotherapy." (PMID 40214422, 2025). "Additionally, USP2a is androgen-regulated and overexpressed in prostate cancer, and its functional inactivation leads to a reduction in FASN protein and an increase in apoptosis." (PMID 39944823, 2025). "For prostate cancer, the FASN inhibitor tvb-2640 is the most representative." (PMID 41281744, 2025). "USP2a interacts with FASN and stabilizes it, promoting the progression of prostate cancer." (PMID 39944823, 2025). "In proliferating cells, however, FASN upregulation may facilitate neoplastic lipogenesis, essential for tumorigenic cell growth, survival, and metabolism in many malignancies, including prostate cancer." (PMID 38112617, 2024). "More recently, there has been some suggestion that epigenetic regulation of FASN may be critical in prostate cancer." (PMID 38112617, 2024). "Finally, it is notable that we were unable to replicate the finding that FASN expression in prostate cancer varies by self-identified race, with higher expression in tumors from BL compared with WH patients seen in two previous studies." (PMID 38112617, 2024). "Prostate cancer patients with FASN protein overexpression have poor biochemical survival." (PMID 39867879, 2024). "Using multivariable models, the HR for prostate cancer metastasis with high FASN expression was greater than 1 for patients with high BMI, but less than 1 for patients with low BMI, though FASN expression level was not statistically significant in either model." (PMID 38112617, 2024). "Interestingly, androgen has been shown to promote lipogenic gene expressions by activating SREBP, and increased fatty acid synthase expressions have consistently been observed in conditions ranging from prostatic intraepithelial neoplasia to prostate cancer." (PMID 37958994, 2023).
prostate carcinoma (continued). "Combination therapy with etomoxir (an irreversible inhibitor of CPT1A), and orlistat (an irreversible inhibitor of lipases and fatty acid synthase) resulted in a synergistic decrease in viability of prostate cancer cell lines (LNCaP and VCaP) and patient-derived benign and prostate cancer cells." (PMID 37110858, 2023). "FASN is also an unfavourable prognostic marker for various cancers including melanoma and high expression values for this gene correlates with advanced stages of colon, breast, and prostate cancer." (PMID 37495601, 2023). "EVs from individuals with prostate cancer typically include cancer-related proteins such as CD9, CD81, and TSG101, as well as Annexin A2, Fatty Acid Synthase (FASN), and a prostate cancer-specific biomarker termed FOLH1 (Prostate Specific Membrane Antigen or PSMA)." (PMID 36059497, 2022). "Additionally, high FASN expression has also been related to poor recurrence-free survival in prostate cancer and a poor prognosis in gastric cancer." (PMID 36555243, 2022). "Likewise, FASN (fatty acid synthase) shows increased expression in cancers such as breast and prostate cancer, and a high activity of FASN has been correlated with poor disease prognosis." (PMID 35008394, 2022). "Moreover, p63 cell survival promoting capabilities engage the actions of FASN and inhibition of FASN induces endoplasmic reticulum stress in prostate cancer cells as well as down-regulates c-MET expression." (PMID 33572160, 2021). "For instance, Ueda et al34 found that FASN expression promoted cell survival and growth of tumour cells in gestational trophoblastic neoplasms, and Nguyen et al35 found that increased intratumoral FASN expression led to more aggressive prostate cancers." (PMID 33626208, 2021). "The present study examined whether inhibition of FASN by orlistat could enhance the therapeutic efficacy of enzalutamide in the human androgen-independent PC3 prostate cancer cell line and ADT in tumor-bearing mice with multiple modules." (PMID 33974005, 2021). "Moreover, uptake of radiolabeled acetate can reflect FASN expression levels and further the sensitivity to FASN-targeted therapy in prostate cancer cell lines as it reduces significantly with the presence of FASN inhibitors." (PMID 34888248, 2021). "FASN depletion leads to decreased RhoU palmitoylation and impaired RhoU activity, and thus the down-regulation of paxillin serine phosphorylation and reduced migration phenotype in prostate cancer." (PMID 34803494, 2021). "Increased FASN triggers lipid accumulation and promotes prostate cancer progression." (PMID 33004065, 2020). "Therefore, we intended to assess the ability of this FASN inhibitor to sensitize prostate cancer cells to radiation in our models." (PMID 33083663, 2020). "Fatty acid synthase (FASN) has been regarded as a prognostic marker in prostate cancer (PCa)." (PMID 32655718, 2020). "The overexpression of FASN can predict a poor prognosis in gastric and prostate cancers." (PMID 32899149, 2020). "Indeed, changes in FASN expression are an early event in the development of prostate cancer and can be identified as the primary source of palmitate in cancer cells." (PMID 32139877, 2020). "In conclusion, this is the first study, to our knowledge, demonstrates that FASN inhibition could sensitise prostate cancer cells to ionising radiation both in vitro and in vivo." (PMID 31527721, 2019). "Nevertheless, whether inhibition of FASN could improve RT outcomes and reverse radiosensitivity of prostate cancer cells is still unknown." (PMID 31527721, 2019). "Here, we hypothesised that orlistat, a FASN inhibitor, could improve RT outcomes in prostate cancer." (PMID 31527721, 2019). "FASN has previously been reported to be a driver of prostate cancer progression." (PMID 29665325, 2018). "The deubiquitinase USP2a is often up-regulated and stabilizes FASN in prostate cancer." (PMID 29996946, 2018).
prostate carcinoma (continued). "Positive correlation between PPARγ and fatty acid synthase (FASN) protein in prostate cancer cell lines and synergism between TZDs and FASN blockers could be shown in prostate cancer cell viability reduction and apoptosis induction." (PMID 30424016, 2018). "Additionally, Lipid synthesis is increased in prostate cancer and Lipogenic enzyme, such as fatty acid synthase (FASN), ATP citrate lyase (ACLY) and acetyl-CoA carboxylase α (ACACA) is highly overexpressed in prostate cancer." (PMID 29163775, 2017). "A high-fat diet (HFD) is attributed to prostate cancer (PCa) progression, but the role FASN on HFD-mediated PCa progression remains unclear." (PMID 26878389, 2016). "However, p300 is also found to be overexpressed in prostate cancer, where it regulates fatty acid synthase expression, lipid metabolism and prostate cancer growth." (PMID 27322556, 2016). "FASN in prostate cancer cells also seems to be mediated by the SREBP pathway." (PMID 26621841, 2016). "According to a previous report, pentagalloyl glucose suppressed rat liver microsomal 5α-reductase activity and expression of the androgen receptor in prostate cells, resulting in a significant reduction in androgen-induced prostate cancer cell growth and fatty acid synthase by pentagalloyl glucose." (PMID 25709710, 2015). "AKT activation increases fatty acid synthase expression in prostate cancer tissue." (PMID 25026288, 2014). "However, dietary fats make up only a fraction of the lipid available to prostate cancer cells, which almost universally upregulate FASN." (PMID 23573093, 2013). "FASN-targeted therapy could be an effective treatment to suppress multiple steps related to tumor progression in prostate cancers selected by [1-11C]acetate PET." (PMID 23741342, 2013). "In this study, we examined whether radiolabeled acetate uptake can predict therapeutic outcome of FASN-targeted therapy using human prostate cancer cell lines to demonstrate applicability of [1-11C]acetate PET as a predictor of FASN-targeted therapy outcome." (PMID 23741342, 2013). "This means that FASN inhibition can provide multipronged benefits for treatment, by suppressing tumor progression and metastasis, as well as preventing androgen-dependent growth in prostate cancers." (PMID 23741342, 2013). "Moreover, recent findings from our group indicate that FASN functions as a metabolic oncogene in prostate cancer by inhibiting the intrinsic pathway of apoptosis." (PMID 19517019, 2009). "Among them, Fatty Acid Synthase (FASN) exhibited the best diagnostic performance in the TCGA validation cohort (AUC = 0.800), outperforming PTGS2 (0.783), ENPP2 (0.621), and CHRM1 (0.605), and was significantly overexpressed in prostate cancer tissues (|log2FC| > 1, adjusted P < 0.05)." (PMID 42228706, 2026). "Since cancer cells have been found to synthesize de novo fatty acids in excess, and prostate cancer becomes aggressive with overexpression of fatty acid synthase, suppressing the levels of de novo fatty acids by elevated ANO7 may offer a mechanism to limit cancerous lipogenesis." (PMID 39923095, 2025). "Finally, we examined the association of FASN protein expression with metastasis in the combined JHU and PCBN cohorts, stratifying by BMI because high FASN was previously shown to be associated with lethal prostate cancer specifically for obese patients." (PMID 38112617, 2024). "Accordingly, a recent study unveiled a novel metabolic function of MYC in regulation of fatty acid synthesis in prostate cancer, indicate that inhibition of fatty acid synthesis by targeting MYC ACLY/ACC1/FASN axis may be a viable strategy for prevention and/or therapy of prostate cancer." (PMID 39538125, 2024). "In addition, the knock-out of FASN gene expression by siRNA process reduced androgen-induced prostate cancer cell proliferation (left) and transcriptional activity of the AR (right) in VCaP prostate cancer cells." (PMID 34944692, 2021).
prostate carcinoma (continued). "In addition, it was reported that androgens were able to induce fatty acid synthase (FASN) expression in prostate cancer, and addition of the anti-androgen might suppress the androgen-induced FASN expression." (PMID 34295247, 2021). "Therefore, FASN is overexpressed in various cancer types such as breast, ovarian, liver, and prostate cancer and serves as a potential oncogene, indicating that FASN may be an attractive therapeutic target for cancer." (PMID 34948233, 2021). "Also, FASN inhibition with shRNA mediates actin cytoskeletal remodeling by decreasing the palmitoylation of Rho GTPases and the downstream activation of Cdc2, resulting in reduced prostate cancer cell migration." (PMID 33166087, 2021). "Thus blocking the activity of FASN in prostate cancer cells is an attractive therapeutic pathway." (PMID 32139877, 2020). "Moreover, androgen, which has been proven to be related to PCa progression, regulates FASN expression and its activity in human prostate cancer cell lines by activating the expression of ubiquitin-specific protease-2a (USP2a), which stabilizes FASN expression to prolong PCa cell survival." (PMID 32655718, 2020). "Moreover, USP2a has been shown to interact with and stabilize FASN in prostate cancer cells." (PMID 30425250, 2018). "Interestingly, FASN is also reported to drive the production of phospholipids, mainly consisting of phosphatidylcholine and phosphatidylethanolamine, partitioning into lipid raft in prostate cancer cells." (PMID 26808816, 2016). "Therefore, FASN-targeted therapy would be effective and [1-11C]acetate PET might be useful as a predictor of FASN-targeted therapy outcome in brain tumors and hepatocellular carcinoma as well as in prostate cancer." (PMID 23741342, 2013). "Thus, metformin effectively blocks lipogenesis by inhibiting activation or expression of lipid biosynthesis enzymes such as acetyl Co-A carboxylase (ACC) and fatty acid synthase (FASN), key regulators of the metabolic reprogramming identified in prostate cancer." (PMID 23573093, 2013). "Also, FASN-targeted therapy could be an effective treatment to suppress multiple tumor essential functions involved in tumor progression and metastasis in prostate cancers selected by [1-11C]acetate PET." (PMID 23741342, 2013). "Hence, FASN is expected to be a good therapeutic target for prostate cancer." (PMID 23741342, 2013). "Thus, this study provides the new treatment strategy of FASN-targeted therapy in prostate cancer." (PMID 23741342, 2013). "Similarly, FASN knockdown by specific siRNAs induces apoptosis in prostate cancer LNCaP cells." (PMID 19352381, 2009). "This study reveals that CCT2 promotes lipid metabolic reprogramming and tumor progression in prostate cancer by cooperating with EIF3F to stabilize FASN, highlighting the CCT2-EIF3F-FASN axis as a potential target for metabolic intervention." (PMID 42231807, 2026). "Among the enzymes discussed, ACLY, ENO, FASN, FAK, and PK are found in EVs from both breast and prostate cancers and contribute to the progression and survival of both cancers." (PMID 40214422, 2025). "A new generation FASN inhibitor, TVB-2640, has shown promising effects in phase I trials in patients with advanced cancer (including prostate cancer, rectal cancer, gastric cancer, etc." (PMID 41281744, 2025). "However, the mechanism of FASN upregulation in prostate cancer remains unclear." (PMID 38112617, 2024). "Both in vitro and in vivo models confirmed that FASN and MAGL, in the presence of FABP5, enhance the metastatic potential of prostate cancer." (PMID 39596205, 2024). "Along with elevated expression of FASN, stearoyl-CoA dehydrogenase (SCD) also exhibited increased expression when SREBP1 was overexpressed in prostate cancer." (PMID 39596205, 2024). "Downregulated IRS1-SREBP1 signaling pathway inhibits its downstream targets, such as FASN and ACC, and inhibits prostate cancer progression." (PMID 36969840, 2023).